HMGA2 (high mobility group AT-hook 2)
Diseases named in the same sentence as HMGA2 in open-access papers (continued):
Sharing a sentence is not in itself a finding about the gene and the disease.
laryngeal squamous cell carcinoma (5 papers, 2017 to 2024). A squamous cell carcinoma that arises from the larynx. "In laryngeal squamous cell carcinoma, HMGA2 expression was negatively related to the levels of miR-98, and the miR-98/HMGA2/periostin (miR-98/HMGA2/POSTN) axis played an important role in reversing EMT." (PMID 38361784, 2024).
myxoid liposarcoma (5 papers, 2009 to 2025). A liposarcoma characterized by the presence of round non-lipogenic primitive mesenchymal cells and small signet ring lipoblasts within a myxoid stoma with a branching vascular pattern. "It has been reported that alteration of HMGA2 is associated with myxoid liposarcoma and takes part in adipogenesis and mesenchymal differentiation." (PMID 33115433, 2020). "This may reflect the intriguing pathogenetic role of HMGA2, which seems to be entirely different from the highly specific gene fusions present in, for example, myxoid liposarcomas." (PMID 26202160, 2015). "At RNA sequencing, significantly elevated expression, compared to myxoid liposarcomas, was seen for TRIO and AMACR in 5p and of CDK4, HMGA2 and MDM2 in 12q." (PMID 28652867, 2017). "Of the selected target genes, AMACR and TRIO in 5p and CDK4, HMGA2 and MDM2 in 12q showed significantly (p < 0.05) elevated expression in relation to myxoid liposarcomas." (PMID 28652867, 2017).
salivary gland neoplasm (5 papers, 2022 to 2025). Tumors of the SALIVARY GLANDS. "Additionally, by highlighting morphological (e.g. striking cytonuclear atypia), immunohistochemical, and molecular characteristics of HMGA2-altered salivary gland tumors, we strive to facilitate recognition in daily diagnostic practice." (PMID 40338436, 2025). "Combining the cases derived from literature and the additional cases from our clinical practice, a total of 37 HMGA2-altered salivary gland neoplasms analyzed for MDM2 amplifications were collected for this analysis." (PMID 40338436, 2025). "In conclusion, we found that immunohistochemical MDM2 expression and MDM2 amplifications are frequent in HMGA2-altered salivary gland tumors with cytonuclear atypia, potentially playing a role in the progression towards malignancy." (PMID 40338436, 2025). "The exact relationship between MDM2 and HMGA2 alterations in salivary gland neoplasms remains unclear, however, we propose a potential mechanism." (PMID 40338436, 2025). "Due to the enriched presence of MDM2 amplification in CXPA with HMGA2 alteration, recognition of this molecular sub-group of salivary gland neoplasms could be potentially informative in the pathologists’ assessment." (PMID 40338436, 2025). "Of note, our NGS panel has routinely identified HMGA2 translocations with diverse downstream partners e.g., HMGA2::PTPRD, HMGA2::WIF1, and HMGA2::ACTR6 in three recent salivary gland tumors (carcinoma ex pleomorphic adenoma) that characteristically harbor HMGA2 rearrangements." (PMID 35798968, 2022). "From the literature search a total of five studies detailing 19 cases of HMGA2-altered, MDM2-analyzed salivary gland neoplasms were included." (PMID 40338436, 2025). "Despite the efficacy of PLAG1 and HMGA2 testing in the diagnosis of pleomorphic adenoma, especially in an unusual site such as the kidney, in the absence of a prior history of salivary gland neoplasm, we did not perform these stains as we do not carry stains for PLAG1 and HMGA2." (PMID 41268216, 2025).
Silver-Russell syndrome (5 papers, 2020 to 2025). Silver-Russell syndrome is characterized by growth retardation with antenatal onset, characteristic facies and limb asymmetry. "We present a 3-year-old male patient with clinical diagnosis of Silver-Russell Syndrome (SRS) associated with a de novo heterozygous deletion of the long arm of the chromosome 12 (12q14.3) encompassing the HMGA2 gene." (PMID 32723361, 2020). "Pathogenic variants in the HMGA2 gene were reported in five patients with Silver-Russell Syndrome (SRS), a variant of uncertain significance in HMGA2 gene described in a boy who had clinical characteristics of SRS." (PMID 40730975, 2025). "Rearrangement of HMGA2 is suggested to drive tumorigenesis by the (dis-)regulatory effect of the HMGA2 protein on PLAG1 and IGF2 expression, a suggestion based on the downregulation of IGF2 expression in patients with Silver-Russel syndrome." (PMID 40338436, 2025). "In undiagnosed patients with clinical features of Silver-Russell syndrome, but negative molecular/genetic analysis, HMGA2 testing should be considered, particularly in those presenting with microcephaly." (PMID 38516887, 2024).
tongue squamous cell carcinoma (5 papers, 2016 to 2025). A squamous cell carcinoma that arises from the tongue. "Through its sponging function, H19 also facilitates the migration and invasion of tongue squamous cell carcinoma cells by suppressing let-7a, leading to the activation of its target gene HMGA2, which, in turn, promotes EMT." (PMID 34572067, 2021). "Taken together, our data suggest that HMGA2 might represent a novel and potentially useful independent biomarker for the prognosis of patients with tongue squamous cell carcinoma." (PMID 26818837, 2016). "In tongue squamous cell carcinoma cells, HOXA distal transcript antisense RNA (HOTTIP) knockdown suppressed the cell migration and EMT by the miR-124-3p/HMGA2 axis, and the H19/let-7a/HMGA2/EMT pathway was also involved in the regulation of EMT." (PMID 38361784, 2024). "In tongue squamous cell carcinoma (TSCC), the long noncoding RNA (lncRNA) H19, by binding to (sponging) let-7a to inhibit its function in repressing let-7 target gene HMGA2, facilitates TSCC cell migration and invasion." (PMID 34572067, 2021).
atherosclerosis (4 papers, 2008 to 2023). A disease characterized by the build-up of fatty material and calcium deposition in the arterial wall resulting in partial or complete occlusion of the arterial lumen. "MiR-663 can target high mobility group AT-hook 2 (HMGA2) to inhibit the proliferation of VSMCs, thereby delaying the development of atherosclerosis." (PMID 38026969, 2023). "Regulating the EV-miR-let7/HMGA2/NF-κB axis can alleviate the inflammatory state of atherosclerosis and provides a new target for the treatment of atherosclerosis." (PMID 35769456, 2022).
colon adenocarcinoma (4 papers, 2016 to 2025). "HMGA2 protein expression was further examined in a colon adenocarcinoma tissue array (BioMax, Rockville, MD, USA)." (PMID 26893968, 2016). "The staining intensity of HMGA2 expression levels were defined on the basis of immunoexpression, as outlined in the IHC protocol, and the colon adenocarcinoma tissues of all grades exhibited positive staining for HMGA2." (PMID 26893968, 2016). "HMGA2 was upregulated in colon adenocarcinoma tissues of different tumor grades." (PMID 26893968, 2016). "We investigated and compared the expression of HMGA2 between tumor and normal tissue in colon adenocarcinoma (COAD) from The Cancer Genome Atlas Program (TCGA), and a higher HMGA2 expression (p = 2.5e−10) was found." (PMID 38845972, 2024).
colorectal tumors (4 papers, 2014 to 2023). "In mammary and colorectal tumors, these invasive HMGA2-positive tumor cells exhibited membrane-to-nucleus re-localization of β-catenin, loss of E-cadherin, increase in levels of vimentin, and an analogous expression of HMGA2 downstream target IGF2BP2." (PMID 32365712, 2020). "Furthermore, HMGA2‐siRNA delivery by CMD‐CS nanoparticles suppresses metastasis of colorectal tumor cells via down‐regulating MMP‐9 and vimentin, and upregulating E‐cadherin that are beneficial in enhancing DOX cytotoxicity." (PMID 36684100, 2023). "We used WT and intestinal epithelial-specific Hmga2 KI mice that were subsequently treated with AOM and DSS to induce colorectal tumors." (PMID 34976223, 2022). "An experiment has prepared CMD‐CS nanostructures for colorectal tumor suppression via siRNA and DOX co‐delivery and the nanosystem exhibited high encapsulation efficiency for both high mobility group A2 (HMGA2)‐siRNA (78%) and DOX (75%) and can induce cell death." (PMID 36684100, 2023).
embryonal carcinoma (4 papers, 2009 to 2025). A non-seminomatous malignant germ cell tumor characterized by the presence of large germ cells with abundant cytoplasm resembling epithelial cells, geographic necrosis, high mitotic activity, and pseudoglandular and pseudopapillary structures formation. "Conversely, we observed a shift from longer-tailed to oligo-adenylated HMGA2 during neuronal differentiation of mouse embryonic carcinoma P19 cells." (PMID 19710908, 2009). "For example, the HMGA2 positivity rate was markedly higher in papillary carcinomas of the kidney (61.7%) than in clear cell (7.2%) and in chromophobe cancers (7.8%), and in yolk sac tumors (95.6%) or embryonal carcinomas (73.5% positive) than in seminomas (18.7% positive) of the testis." (PMID 40518465, 2025).
head and neck cancer (4 papers, 2018 to 2024). A primary or metastatic malignant neoplasm affecting the head and neck. "RNA sequencing analysis of tumor and normal samples has shown that HMGA2 expression is upregulated in most cancers, including head and neck cancer." (PMID 35388172, 2022).
hepatoblastoma (4 papers, 2022 to 2024). Hepatoblastoma (HB) is a malignant hepatic tumor and is the most common pediatric liver cancer.
myelodysplastic syndrome (4 papers, 2020 to 2025). A clonal hematopoietic disorder characterized by dysplasia and ineffective hematopoiesis in one or more of the hematopoietic cell lines. "Translocations, duplications, and amplifications involving HMGA1 or HMGA2 have been reported in solid tumors, myeloid malignancies, such as myelodysplastic syndromes (MDS), and other hematologic malignancies, although such events are relatively infrequent." (PMID 40076747, 2025). "Notably, the identified stress-regulated Hmga2 gene signature is activated in hematopoietic stem progenitor cells of human myelodysplastic syndrome patients." (PMID 38811851, 2024). "The overexpression of HMGA2 associated with the 3′-UTR deletion was found not only in MPN patients but also in those with myelodysplastic syndrome (MDS) and MDS/MPN as well as in patients with paroxysmal nocturnal hemoglobinuria (PNH)." (PMID 32503270, 2020).
ovarian serous carcinoma (4 papers, 2018 to 2026). "In high‐grade serous ovarian carcinoma (HG‐SOC), high expression of miR‐182 promotes tumorigenesis by targeting Breast Cancer Gene 1 (BRCA1), High Mobility Group AT‐Hook 2 (HMGA2), and Metastasis Suppressor 1 (MTSS1) genes." (PMID 39617640, 2024). "Another study assessed the protein expression of E-CADH, N-CADH, P-cadherin, ZEB1, HMGA2, RAB25, CD24, NCAM, SOX11, and VIM in 100 tubo-ovarian serous carcinoma effusions and found a limited prognostic role of the markers alone or in combination." (PMID 34070214, 2021).
ovarian tumors (4 papers, 2015 to 2021). "One can reasonably assume that dysregulation of these miRNAs is a cause leading to HMGA2 upregulation in ovarian tumors." (PMID 28423547, 2017). "However, the mechanisms underlying regulation of HMGA2 in ovarian tumors are currently unclear." (PMID 30474570, 2018). "We report a study of 155 ovarian tumors (30 sex-cord stromal tumors, 22 borderline tumors, and 103 carcinomas) analyzed for HMGA2 expression as well as the expression of two miRNAs targeting this gene, let-7a and miR-30c." (PMID 28423547, 2017). "The high frequency of downregulation of these miRNAs found indicates that this is a significant way of obtaining HMGA2 deregulation in ovarian tumors." (PMID 28423547, 2017). "To obtain more insight into the role of HMGA2 and its possible regulation by miRNAs in ovarian malignancies, we analyzed a series of 155 ovarian tumors of different histologies for HMGA2 gene expression as well as for the expression of two miRNAs targeting HMGA2, let-7a and miR-30c." (PMID 28423547, 2017). "In a previous study, we found HMGA2 expressed in 74% of the ovarian tumors examined." (PMID 28423547, 2017). "According to studies, oncogenic miR-182 expression is upregulated in high-grade ovarian tumors, resulting in proliferation and progression of cancer cells by enhancing the BRCA1/HMGA2 dysregulation." (PMID 34721577, 2021). "The proliferative subtype was identified by the overexpression of transcription factors HMGA2 and SOX11, proliferation marker genes such as MCM2 and PCNA, and underexpression of MUC1 and MUC16, which are known ovarian tumor marker genes." (PMID 25611546, 2015). "This does not seem to be the case for ovarian tumors as both FHIT and HMGA2 were found expressed in all tumors analyzed." (PMID 28423547, 2017).
pleomorphic adenomas of the salivary gland (4 papers, 2014 to 2025). "Fusion genes involving HMGA2 have also been detected in various tumor types such as lipomas leiomyomas, pleomorphic adenomas of the salivary gland, cervical polyps and hemangiopericytomas." (PMID 36439507, 2022). "In pleomorphic adenomas of the salivary glands (PASG) recurrent chromosomal rearrangements affecting either 8q12 or 12q14∼15 lead to an overexpression of the genes of the genuine transcription factor PLAG1 or the architectural transcription factor HMGA2, respectively." (PMID 24516594, 2014).
renal carcinoma (4 papers, 2024 to 2026). A carcinoma arising from the epithelium of the renal parenchyma or the renal pelvis. "NUF2 acts as an oncogene in renal cancer by affecting the expression of HMGA2 by KDM2A-mediated H3K36me2 demethylation." (PMID 39242581, 2024).
Sepsis (4 papers, 2018 to 2023). Sepsis is defined as life-threatening organ dysfunction caused by a dysregulated host response to infection. "miR-98 protects sepsis mice from cardiac dysfunction, liver and lung injury by negatively mediating HMGA2 via the inhibition of the NF-κB signaling pathway." (PMID 35720285, 2022). "The literature also revealed that miR-98 negatively regulates HMGA2 by inhibiting the NF-κB signaling pathway to protect mice from sepsis-mediated lung damage." (PMID 34092219, 2021). "Hmga2, which is often seen upregulated in human sepsis and which has been shown to be involved in immune activator functions and tissue damage, increased over time in our endotoxemia model." (PMID 29651289, 2018).
thyroid (4 papers, 2003 to 2025). "The interaction between HMGA2 and the AP-1 transcriptional complex is considered to be responsible for the activation of genes whose expressions are associated with carcinogenesis, since thyroid neoplastic transformation is associated with a drastic increase in AP-1 activity." (PMID 14647145, 2003). "Recently HMGA2 expression has been shown to indicate thyroid malignancy and can thus be considered marking the dedifferentiation of thyroid epithelium." (PMID 22050638, 2011). "We have recently demonstrated that HMGA2 plays a prominent role in the aggressiveness of PTC cell lines by facilitating cell invasion, however the complete role of HMGA2 in thyroid tumorigenesis and the exact mechanism by which it exerts its effects remains poorly understood." (PMID 40004107, 2025).
-thalassaemia (3 papers, 2010 to 2022). "The recent report of a clonal expansion from integration of Lentivirus vector in the DNA-binding protein HMGA2 (high mobility group AT-hook 2) gene in a patient of the gene therapy trial for thalassemia in France imposes however further caution." (PMID 21078154, 2010).
acromegaly (3 papers, 2016 to 2021). Acromegaly is an acquired disorder related to excessive production of growth hormone (GH) and characterized by progressive somatic disfigurement (mainly involving the face and extremities) and systemic manifestations. "Additionally, whole genomic regions of seven genes (HMGA2, FGFR4, PTTG1, RB1, GNAS, AIP, GPR101) associated with acromegaly were added to the profiling target." (PMID 34400688, 2021).
African sleeping sickness (3 papers, 2020 to 2025). "Suramin, an anti-trypanosomal drug used to treat African sleeping sickness and river blindness, has recently been identified as a potent inhibitor of HMGA2-DNA interactions." (PMID 40004107, 2025). "On the other hand, suramin, an antiparasitic drug known for treating African sleeping sickness, was recently discovered to be a potent inhibitor of HMGA2-DNA interactions." (PMID 40004107, 2025). "After screening the LOPAC1280 compound library, we found that suramin, a highly negatively charge anti-parasitic drug that is used to treat African sleeping sickness and river blindness, is a potent inhibitor of HMGA2-DNA interactions." (PMID 33139812, 2020). "In this context, the use of HMGA2 inhibitors, such as suramin, an antiparasitic drug used for the treatment of African sleeping sickness but also a potent inhibitor for HMGA2-DNA interactions, showing anti-cancer and anti-metastasis activities, is very promising." (PMID 37445942, 2023).
anaplastic cancer (3 papers, 2011 to 2021). "In anaplastic cancer, HMGA2 expression was also found to be elevated in most cases (80%, p = 0.000017)." (PMID 33440616, 2021). "Two specimens of anaplastic carcinoma also featured an increased level of HMGA2 mRNA." (PMID 31660895, 2019).
Anxiety (3 papers, 2016 to 2022). Intense feelings of nervousness, tension, or panic often arise in response to interpersonal stresses. "Later studies confirmed that HMGA2 was implicated in smaller body size in the dog, as well as possible behavior effects on separation anxiety, touch-sensitivity, owner-directed aggression, and dog rivalry." (PMID 35617214, 2022). "Thus, in an attempt to study if Hmga2 inactivation in mice affects behavior, a 30-min open-field test was performed to evaluate exploratory and anxiety/stress‐linked behavior in the mouse model." (PMID 34878116, 2022).
Breast Invasive Carcinoma (3 papers, 2019 to 2022). "Using the same cutoff for HMGA2-high expression, approximately 13.0% (23 of 177) of tumor samples annotated as TNBC in The Cancer Genome Atlas (TCGA) Breast Invasive Carcinoma data set had high expression of HMGA2 after adjustment with the ComBat algorithm." (PMID 36568239, 2022).
carcinoid (3 papers, 2014 to 2022). "Accordingly, HMGA2 protein expression was entirely devoid in the slow growing carcinoids in our study and HMGA2 protein levels in stage I patients were associated with progression free survival supporting the role of HMGA2 as a marker of aggressiveness." (PMID 26858029, 2016). "let-7 overexpression inhibited growth of carcinoid cell lines, and let-7 inhibition increased protein content of the transcription factor BACH1 and its targets MMP1 and HMGA2, all known to promote bone metastases." (PMID 25546138, 2014).
clear cell carcinomas (3 papers, 2017 to 2025). "High levels of HMGA2 RNA expression occurred in a small subset (43 of 480) clear cell carcinomas and were closely associated with poor survival (p < 0.0001)." (PMID 40518465, 2025). "The lowest levels of HMGA2 expression were detected in clear cell carcinomas (mean = 1.8; median = 0.5)." (PMID 28423547, 2017). "HMGA2 was found expressed at high levels in most samples analyzed, with clear cell carcinomas as the only exception." (PMID 28423547, 2017).